GAD1 (glutamate decarboxylase 1)
Diseases named in the same sentence as GAD1 in open-access papers (continued):
Sharing a sentence is not in itself a finding about the gene and the disease.
Anxiety (continued). "In addition, we also found that GAD1 “Nervousness or anxiety”, GAD4 “Trouble relaxing”, and GAD3 “Worry too much” were high in EI and were thus identified as central symptoms." (PMID 38347882, 2024). "Decrease in anxiety like behavior and increase in expression of gad1 in brain and gut." (PMID 37324381, 2023). "GAD1 has previous genetic evidence in anxiety and panic disorders." (PMID 36878964, 2023). "Another speculation for hypoactivity is that it is a manifestation of increased anxiety in Gad1−/− rats." (PMID 33293518, 2020). "On the other hand, the studies on neuroticism and anxiety demonstrated GAD1 SNP associations even without considering gender effects." (PMID 22662185, 2012). "However, the role of Gad1 (and GAD67) in anxiety and fear is unclear." (PMID 33325157, 2021). "In summary, we observed enhancement of anxiety-like behavior (increased thigmotaxis in the open field and increased avoidance of open arms in the elevated plus maze), nest building, and social dominance following the miRNA silencing of Gad1 in NPY+ interneurons in adolescent mice." (PMID 30024942, 2018). "Symptom network analysis reveals a shift in centrality patterns: while depressive symptoms were dominant at T1, anxiety symptoms—particularly GAD3 (Excessive Worry), GAD2 (Uncontrollable Worry), and GAD1 (Nervousness), became more central at T2." (PMID 40893605, 2025). "In addition, GAD6 “Irritable”, GAD5 “Restlessness” and GAD1 “Nervousness or anxiety” showed the highest bridge strength linking cognitive impairment and anxiety symptoms, suggesting that these symptoms should be treated first to reduce and prevent comorbidities of anxiety and cognitive impairment." (PMID 39234623, 2024). "The bridge expected influence index indicated that GAD5 (Restlessness), GAD1 (Nervous), and PHQ9 (Death) were the bridge symptoms that drove the comorbid depression and anxiety symptoms." (PMID 36408014, 2022). "Not surprisingly, the LBRD standard decoction corrected the increased miR-144-3p and miR-495, whereas inhibited Gad1, VGAT, and Bdnf mRNAs and protein expression in the chronic stress-mediated depression and anxiety model." (PMID 34674715, 2021). "Meanwhile, among the anxiety symptom community, node GAD3 (“Worry too much”) had the most direct connection with node GAD4 (“Relaxing Trouble”), followed by the connection between nodes GAD1 (“Nervousness”) and GAD2 (“Uncontrollable Worrying”)." (PMID 38026317, 2023). "In addition, Dox-treated Gad1tTA/STOP−tetO mice walked a long time in the wall side and a short time in the center region compared with Dox-treated Gad1+/+ mice, indicating that Gad1tTA/STOP−tetO mice exhibited anxiety-like behavior in the open-field test." (PMID 33413507, 2021). "Although Gad1 KO rats showed significantly reduced locomotor activity in the open field test, their anxiety‐like behaviors in the elevated plus‐maze test were not altered." (PMID 33325157, 2021). "Therefore, we suggest the possibility that the global reduction in GAD1 transcript and GAD67 protein in the brain might be related to the occurrence of anxiety symptoms frequently comorbid in several psychiatric disorders." (PMID 33413507, 2021). "Students’ grades at the bottom 27% (poor academic group) of 16 nodes demonstrated that 73 out of 120 edges were non-zero, and the edge of GAD-1 (nervousness) and GAD-2 (uncontrolled worry) showed the strongest connection in the anxiety symptoms." (PMID 36925600, 2023). "This shift was accompanied by stronger links with anxiety-related symptoms such as GAD1(Nervousness) and GAD2 (Uncontrollable Worry), suggesting that suicidal ideation may increasingly align with an anxiety-based symptom profile rather than with classical depression." (PMID 40893605, 2025).
depression (70 papers, 2010 to 2026). "Changes in GABAergic system were identified by assessing changes in the gene expression of GABAA or GAD1 in key regions associated with depression neurocircuitry, including mPFC, DStr, NAc, HPC, LHb, VTA, and SN." (PMID 40021746, 2025). "GAD1 has been linked to a latent phenotype based on common genetic factors underlying neuroticism, depression, and anxiety disorders." (PMID 24489727, 2014). "In unipolar depression, which is comorbid with panic disorder, a Finnish association study found alleles of the GAD1 polymorphisms rs12185692 (upstream) and rs769407 (in the sixth intron) to go along with disease only in females." (PMID 22662185, 2012). "In a recent association study in depression, which is highly comorbid with panic disorder, GAD1 risk allele associations were restricted to females." (PMID 22662185, 2012). "Since depression as well as panic disorder are both more prevalent among females, this striking gender difference prompted us to investigate whether gender-specific associations of GAD1 variants are also detectable in panic disorder." (PMID 22662185, 2012). "The emergence of GAD1 as a hit in both algorithms implies a major role in depression pathophysiology as well as in the serotonergically mediated antidepressant action." (PMID 32612257, 2020). "In CUMS‐induced depression‐like group, the Gad‐1, VGAT and GAT‐3 mRNA expression in the NAc tissue were significantly decreased than that of control mice (both P < .01)." (PMID 31430030, 2019). "A systematic review found that major histocompatibility complex, class I-related gene polymorphisms, and glutamate decarboxylase (GAD) genes (GAD1 and GAD2) contributed to the development of depression." (PMID 31281445, 2019). "The decreased expressions of mRNAs in CUMS-induced depression mice include Slc6a11, Hap1, Gad1, Gad2, Gng4, Slc32a1, Doc2g, Slc32a1, Magel2, Prkcd, Ngfr, Dusp1, Th, Itih3, Cacna2d2, Arc, Mbp, Peg10, Fos, and so on." (PMID 27427907, 2016). "Given the overlap between the genetic underpinnings of self-esteem, neuroticism, and depression, it is conceivable that GAD1 and GABA play an important role in self-esteem, too." (PMID 24489727, 2014). "Another study revealed that DNMT1 mediates chronic pain-related depression by promoting methylation at the CpG-rich glutamate decarboxylase 1 (Gad1) promoter and downregulating Gad67 expression, which affects GABAergic neuronal activation in the central amygdala." (PMID 40508158, 2025). "After LBRD standard decoction administration, four differentially expressed miRNAs, rno-miR-144-3p, rno-miR-495, rno-miR-34c-5p, and rno-miR-24-3p, and six differentially expressed mRNAs, Calml4, Ntrk2, VGAT, Gad1, Nr1d1, and Bdnf overlapped in the in vivo/vitro depression model." (PMID 34674715, 2021). "Expression studies found reduced GAD1 expression in brain samples from depression patients." (PMID 32612257, 2020). "Results from the STAR*D study showed a marginal association of treatment-resistant depression with NFIB (p = 0.068) but not with GAD1 (p = 0.23) and TBC1D9 (p = 0.27)." (PMID 32612257, 2020). "Those GAD1 SNPs that were not (rs12185692) or only marginally (rs769407) associated with neuroticism revealed female-specific associations with depression." (PMID 22662185, 2012). "qPCR results showed that knockdown of Homer1 improved the expression of inflammation‐related markers IL‐1β, TNF‐α, IL‐10, and depression‐related markers ERCCL2, SLC6A4, and GAD1 in primary neurons, both in the PTSD group and in the TBI+Hcort group." (PMID 39665190, 2025). "In depression, altered chromatin accessibility have been observed at BDNF, GAD1, NR3C1 in response to stress." (PMID 41234420, 2025). "Studies in depression show decreased H2K9ac at BDNF, in schizophrenia where H3K27me3 is modified at GAD1, in PTSD with repressive marks on FKBP5, and in addiction where changes in H3 acetylation impact reward circuits." (PMID 41234420, 2025).
depression (continued). "More recently, in mice exposed to chronic unpredictable mild stress, gene and protein expression of GAD1, VGAT, and GAT3 were reduced in the nucleus accumbens, an area targeted in the comorbidity of depression and addiction." (PMID 38391931, 2024). "Our results showed that the expression level of GAT‐3, Gad‐1 and VGAT mRNA and protein significantly decreased in the NAc tissue from CUMS‐induced depression‐like mice than that of control mice." (PMID 31430030, 2019). "The decreased level of Gad1 and VGAT expression has already been reported in either depressed patients or depression animal model, which are in line with our observations." (PMID 31430030, 2019). "The expressions of Hbb-b1 and Nr1d1 are raised, as well as the expressions of Gad1, Mbp and Slc6a11 are decreased in CUMS-induced depression mice, compared to the control mice (p<0.01)." (PMID 27427907, 2016). "In our biomarker analysis, expression of GAD1, NFIB, and TBC1D9 showed associations with response status, remission status, and improvement in depression scale, respectively, but not with treatment resistance." (PMID 32612257, 2020). "In addition to the reduction in SST in depression, there is also a deficit in expression of the GABA-synthesizing enzymes glutamate decarboxylase 1 (GAD1, also known as GAD67) and GAD2 (also known as GAD65)." (PMID 27660699, 2016).
epilepsy (58 papers, 2004 to 2026). A brain disorder characterized by episodes of abnormally increased neuronal discharge resulting in transient episodes of sensory or motor neurological dysfunction, or psychic dysfunction. "In conclusion, this case series reports distinct phenotypical features caused by GAD1 variants, including early-infantile onset epilepsy, severe developmental delay and muscle weakness." (PMID 32705143, 2020). "The unc-47 gene, homologous to human GAD1, encodes a key enzyme for GABA synthesis, and its dysregulation is associated with neurodegenerative diseases, epilepsy and autism." (PMID 40863938, 2025). "In conclusion, we demonstrated that GAD1 deficiency in rats results in abundant SWDs in EEG data from an early age, comparable to other epilepsy-model rodents." (PMID 37830095, 2023). "Using a unique feature of certain in vitro epilepsy models, we show that without this glutamatergic feedback, intense activation of interneurons causes parvalbumin and glutamate decarboxylase 1 mRNA expression to increase." (PMID 30110232, 2018). "However, whether these Gad1 (–/–) homozygous knockout rats show any other neurological symptoms, such as epilepsy, remains to be determined." (PMID 37830095, 2023). "Though it is possible that GAD1 variant status might modify clinical presentation within the two branches of the family described here, we note that these clinical features, including, epilepsy were not reported within the family." (PMID 33634263, 2021).
cerebellar ataxia (51 papers, 2004 to 2025). A neurological syndrome characterized by clumsy and uncoordinated movement of the limbs, trunk, and cranial muscles. "In humans, autoantibodies against GAD1 have been associated with cerebellar ataxia." (PMID 37476399, 2023).
autism (31 papers, 2011 to 2026). Persistent deficits in social interaction and communication and interaction as well as a markedly restricted repertoire of activity and interest as well as repetitive patterns of behavior. "HOX genes (HOXD1) map into human chromosome 2 region (2q31–2q33), where GAD1 and DLX2 also reside, and while linkage to autism is weak for the genes in this region (e.g., GAD1), the sheer proximity could potentially signify transcriptional coregulation." (PMID 39758604, 2025). "Our study contributes to a plethora of evidence that implicates GAD1 in autism, but adds unique knowledge on the role of GAD1 at the embryonic development stage of the condition and indicates that the gene is subject to altered epigenetic regulation in the early stages of neurodevelopment." (PMID 36012452, 2022). "E2 increases GAD-67+ (also known as GAD1+) GABAergic interneurons in a rat model of IS and elevates parvalbumin expression in a Pvalb KO model of autism with rescue of aberrant phenotypes." (PMID 32033960, 2020). "In prior studies, GAD1 and GAD2 have been shown to be reduced in parietal and cerebellar cortex in autism and GABA receptor density is reduced in post-mortem autism cerebral cortex." (PMID 29859039, 2018). "Next, we analyzed whether the expression of two genes (Gad1, hyper-methylated at CpG in female pups and Park2, hyper- and hypo-methylated at both CpG and non-CpG sites in male and female pups) that play a role in neuronal pathways including autism are altered at the protein level." (PMID 27199632, 2016). "In addition to proinflammatory genes, there are also reports of reduced expression of several key neuronal genes such as RELN, SLC1A2, GAD1, TSC1 and HAP1 in autism or autism spectrum disorders, which have not been causally linked to neuro-inflammation in autism." (PMID 38994948, 2024).
Cognitive impairment (21 papers, 2011 to 2025). Abnormal cognition is characterized by deficits in thinking, reasoning, or remembering. "Glutamate decarboxylase 1 (GAD1) mRNA expression, is associated with cognitive impairment, was quantified by a real-time polymerase chain reaction." (PMID 33920851, 2021). "Of these, RELN and GAD1 have been clearly associated with cognitive impairment." (PMID 36406755, 2022). "Therefore, cognitive impairments in Gad1−/− rats may be partially explained by loss of GAD67 and subsequent impaired GABAergic transmission." (PMID 33293518, 2020). "SCZ patients exhibited defective expression of histone H3K4-trimethylation (H3K4me3) and GABAergic promoter subsets of genes (GAD1, GAD2, NPY, and SST) in the prefrontal cortex, all of which are strongly associated with cognitive impairment." (PMID 36406755, 2022). "The genes of cognitive impairment modified by DNA methylation include GAD1, BDNF, DRD3, DRD4, and 5HTR1A." (PMID 36406755, 2022). "The results from the behavioral tests strongly suggest that Gad1−/− rats had spatial cognitive deficits, which can be affected by abnormalities in adult neurogenesis." (PMID 33293518, 2020). "The genes of cognitive impairment modified by histone include GAD1, GAD2, NMDAR, CACNA1H, and BDNF." (PMID 36406755, 2022). "This can make a difference in detecting possible cognitive impairments of Gad1 knockout animals." (PMID 33293518, 2020). "Taken together, the results suggest that Gad1 KO rats could provide a novel model covering not only cognitive deficits but also other aspects of the disorder." (PMID 33293518, 2020). "Different effects on working memory between our global Gad1 KO rats and the cKO/KD mice also may be attributed to differences in the severity of cognitive impairment." (PMID 33293518, 2020). "In addition to cognitive impairments, Gad1−/− rats showed characteristic alterations in activity." (PMID 33293518, 2020).
Parkinson disease (16 papers, 2010 to 2025). A progressive degenerative disorder of the central nervous system characterized by loss of dopamine producing neurons in the substantia nigra and the presence of Lewy bodies in the substantia nigra and locus coeruleus. "In support of this hypothesis, gene-based therapies using GAD1 to modulate neuronal signaling are being used to treat patients with Parkinson’s disease and similar approaches could be evaluated in patients with ALS 36,37." (PMID 34548578, 2021). "For example, the level of hypomethylation of glutamate decarboxylase 1 (GAD1) in Parkinson's disease is higher than in healthy individuals, and/or the DNA hypermethylation of norepinephrine is higher in Parkinson's disease." (PMID 37901797, 2023).
anxiety disorder (13 papers, 2012 to 2025). A category of psychiatric disorders which are characterized by anxious feelings or fear often accompanied by physical symptoms associated with anxiety. "They found that variations in the GAD1 gene may affect susceptibility across a range of anxiety disorders." (PMID 35686186, 2022). "Polymorphisms in Gad1 have been linked to anxiety disorders." (PMID 30024942, 2018). "Although not exclusively studied in SAD, the evidence supporting the notion that impairments of GAD may be involved comes from previous studies showing that certain polymorphic variants of GAD1 were associated with an increased risk for developing anxiety disorders (including SAD)." (PMID 40725163, 2025). "Considering significant decreases in Gad67 neurons in the hippocampus and basolateral amygdala of Ulk4+/tm1a mice, and the correlating functions of GAD1 in humans, it will be interesting to investigate if polymorphisms of the ULK4 link to anxiety disorders in patients." (PMID 29391390, 2018).
Alzheimer disease (12 papers, 2014 to 2025). A progressive, neurodegenerative disease characterized by loss of function and death of nerve cells in several areas of the brain leading to loss of cognitive function such as memory and language. "Early expression of intraneuronal amyloid-β (not phospho-tau) and inflammatory and glycosylation pathway transcripts distinguish neocortical RORB+ and GAD1+ neurons selectively vulnerable to neurodegeneration in Alzheimer’s disease." (PMID 40467545, 2025).
ischemia (10 papers, 2010 to 2023). A hypoperfusion of the BLOOD through an organ or tissue caused by a PATHOLOGIC CONSTRICTION or obstruction of its BLOOD VESSELS, or an absence of BLOOD CIRCULATION. "GAD1 mRNA expression in the hippocampus was lower in the ischemia group (0.06 ± 0.01) than in the sham group (0.10 ± 0.01)." (PMID 33920851, 2021). "GAD1 expression tended to increase slightly more in the ischemia + tacrine group (0.07 ± 0.01) than in the ischemia + saline group (0.06 ± 0.01, p = 0.83)." (PMID 33920851, 2021). "However, the present study further raises questions on the occurrence of a significantly decreasing mRNA level for Gad1 4 h after ischemia, which could not be detected on the immunofluorescence analysis at this early stage, but on the later time point." (PMID 31089963, 2019).